STAT3 (signal transducer and activator of transcription 3)
Diseases named in the same sentence as STAT3 in open-access papers (continued):
Sharing a sentence is not in itself a finding about the gene and the disease.
breast cancer (continued). "Our results are consistent with this in the context of PD-L1 status and with previously reported correlation of PD-L1 expression in breast cancer with cytotoxic immune response genes and immune-related pathways and features (e.g., IFN-α, IFN-γ, STAT3, and TNFα)." (PMID 39656429, 2025). "MDSCs increase CSC properties by activation of STAT3 and NOTCH signaling in breast cancer." (PMID 40647402, 2025). "A study analyzing tissue samples from breast cancer patients, both with and without lymph node metastasis, reported a correlation between increased levels of phosphorylated STAT3 (phospho‐STAT3) and improved short‐ and long‐term survival rates." (PMID 40166646, 2025). "In our previous study, Co-IP and immunofluorescence results confirmed the interaction between YAP and STAT3 in IEC-6 cells, which is consistent with one study suggesting that YAP interacted with STAT3 to promote macrophage M2-type polarization induced by breast cancer cell supernatant." (PMID 40861465, 2025). "For example, when stimulated with EGF, PLSCR1 not only directly binds to the promoter of STAT1, but also enhances STAT3’s binding to the STAT1 promoter in breast cancer cells, leading to the transactivation of STAT1 and basal-like breast cancer (BLBC) progression." (PMID 40248364, 2025). "Notably, activation of TrkA enhances STAT3 activity, promoting the transcription of related genes in TNBC and HER2‐overexpressing breast cancers, thereby supporting the growth of breast cancer stem cells." (PMID 39558881, 2024). "Another study involving ExomiR-155 showed that it inhibits SOCS6, activating the JAK2/STAT3 signaling pathway leading to the proliferation and differentiation of SKBR3 cells and MCF-7, which ultimately results in breast cancer cells becoming resistant to tamoxifen." (PMID 38455764, 2024). "In MDSCs of breast cancer infiltration, phosphorylated STAT3 can activate the non-canonical NF-κB signaling pathway, leading to the phosphorylation of p100 and the nuclear translocation of p52-RelB." (PMID 38822095, 2024). "Our data showed that this compound reduced the expression of IL-6 mRNA and STAT3, which promote proliferation, metastasis, invasion, and angiogenesis in breast cancers, and could result in the suppression of the NF-kB/IL-6/JAK2/STAT3 signaling pathway." (PMID 38673967, 2024). "lycorine suppressed migration and invasion by inhibiting the STAT3 signaling pathway in osteosarcoma cells and breast cancer cells, while also enhancing the expression of the negative STAT3 regulator, SHP-1." (PMID 39245716, 2024). "In line with this, previous reports have indicated a potential benefit of STAT3 inhibition in Her2-enriched breast cancer, although clinical validation is still lacking." (PMID 39001513, 2024). "CHI3L2 is expressed both in the cytoplasm of cancer cells and in macrophages and may regulate STAT-3 and ERK1/2 phosphorylation in breast cancer cell lines." (PMID 39557919, 2024). "In addition, similar to breast cancer, in PTC, TRIM14 facilitates the ubiquitination and degradation of SOCS1, a negative regulator of STAT3 activation." (PMID 39719450, 2024). "Furthermore, the JAK/STAT3 mediates enhancement of FAO, thereby promoting the cancer stem cell self-renewal and chemoresistance in several cancer types including breast cancer, lung cancer and gastric cancer." (PMID 38245798, 2024). "Additionally, VEGF/VEGFR2 signaling has been shown to promote STAT3 activation leading to self-renewal of breast cancer cells in vitro and VEGFA induces LEC migration and tube formation via STAT3 signaling." (PMID 38218743, 2024). "Recent studies suggest that ETV7 controls breast cancer inflammation by controlling the TNF-α axis and cross-talking with STAT3—an inflammation regulator—suggesting that VD3-GNPs therapeutically alter these pathway markers via ETV7, which is a challenge for future studies." (PMID 38791386, 2024).
breast cancer (continued). "In breast cancer, TRIM1 expression has been reported to be up-regulated via MORC4/STAT3-mediated transcription activation, which might be the reason that leaded to circTRIM1 overexpression in chemoresistant TNBC cells and tissues." (PMID 38755678, 2024). "In breast cancer, SCARA5 blocks ERK1/2, Akt, and STAT3 pathway activities." (PMID 38891888, 2024). "TQ significantly reduced both constitutive and inducible phosphorylation of STAT3 in breast tumor tissue but did not affect STAT5 in breast cancer." (PMID 38397437, 2024). "In breast cancer-derived MDSCs, STAT3-induced activation of the non-canonical NF-κB signaling pathway promoted an immunosuppressive microenvironment by regulating the expression of IDO15." (PMID 38822095, 2024). "Using three breast cancer cell lines, we found that the effect of LDHC targeting on tumor cell survival was negatively impacted by the activation of the STAT3 pathway in some cell lines and could be restored by STAT3 inhibition." (PMID 39001513, 2024). "The phosphorylation of STAT3 in MDSCs infiltrated by breast cancer can induce the activation of the non-classical NF-kB signaling pathway and promote the formation of the p52-RelB dimer." (PMID 38822095, 2024). "In breast cancer dormant cells, the interaction of DDR1 with collagen I regulates self-renewal and metastatic reactivation via Signal Transducer and Activator of Transcription 3 (STAT3) activation." (PMID 39682261, 2024). "MDSCs in breast cancer induce IL-6-dependent STAT3 phosphorylation and NOTCH activation via nitric oxide (NO), resulting in prolonged STAT3 activation, which enhances the stem cell-like properties of breast cancer stem cells and inhibits T-cell activation to promote tumor formation." (PMID 38609997, 2024). "To examine whether CAPN5 cleaves c-Myc and STAT3 in vitro, we produced recombinant murine CAPN5 proteins with a C-terminal Myc-His (MH) tag in the human breast cancer cell line MCF-7." (PMID 39357823, 2024). "In the MDA-MB-231 breast cancer cell line (ER−/PR−/HER2−, EGFR+), curcumin reduced ERK phosphorylation, while apigenin inhibited tyrosine phosphorylation of HER2 and reduced the expression of phospho-JAK1 and phospho-STAT3." (PMID 39519572, 2024). "To investigate whether the inhibition of STAT3 by LINC01929 knockdown is mediated by TNF, we discovered that the cytokine TNF‐α is capable of activating both the TNF pathway and STAT3 in breast cancer cell lines." (PMID 39586790, 2024). "Another group showed an important crosstalk axis where CAFs secrete IL-6, and breast cancer cells develop radioresistance through CAF mediated activation of the STAT3 pathway; blocking this IL-6-STAT3 axis decreased breast cancer growth and increased susceptibility to treatment." (PMID 38572312, 2024). "In in vitro models of breast cancer, the role of leptin on proliferation, migration, epithelial-mesenchymal transition (EMT), and cell invasion by activating signaling pathways such as ERK, STAT3, and FAK-Src has been described." (PMID 38228661, 2024). "Additionally, we have identified the deletion of EGR3 to be a crucial genetic alteration in canine mammary cancer, which regulates the JAK1/STAT3 signaling pathway." (PMID 38338065, 2024). "Through human kinase arrays, we found that STAT3 signaling was activated in EGFR+ HER2+ breast cancer and that the inhibition of STAT3 led to the downregulation of SUSD2 levels, indicating that STAT3 was responsible for upregulated SUSD2 levels in EGFR+ HER2+ breast cancer." (PMID 39791720, 2024). "In breast cancer, particularly TNBC, JAK2/STAT3 signaling is known for its excessive activation." (PMID 38699644, 2024). "Moreover, our results obtained in functional in vitro model suggest, that CHI3L2 is involved in IDC basal B breast cancer cells, represent in our studies by BT-549 cells, in modulation of ERK1/2 and STAT-3 phosphorylation patchways." (PMID 39557919, 2024).
breast cancer (continued). "DepMap portal plots using publicly available data derived from human breast cancer cell lines and Gepia2 plots using publicly available tumor samples from patients with breast cancer demonstrated that TNBC subtypes show high expression levels of PTK2 (FAK), EGFR, ITGA5, ITGB1, and STAT3." (PMID 38315147, 2024). "Furthermore, STAT3 inhibitors such as C188-9 and Stattic not only reduced SUSD2 levels, but also suppressed cell growth and cell cycle progression in EGFR+ HER2+ breast cancer cell lines." (PMID 39791720, 2024). "Finally, studies also suggest that metformin can inhibit several STAT3-related signaling pathways known to be involved in breast cancer, including IL-6/JAK2/STAT3 signaling." (PMID 38543182, 2024). "Induction of the TEM from melanoma cells, transfer of miRNAs supporting 1-integrin-NF-kB signaling from metastatic liver cancer cells, improvement of breast cancer cell motility and ECM remodeling pathways, and activation of SOCS1/JAK2/STAT3 signaling from melanoma cells." (PMID 39187523, 2024). "Thus, LDHC-targeted therapy could be a viable therapeutic approach for a subset of breast cancer patients, particularly patients with basal-like breast cancer, whereas patients carrying Her2-enriched tumors may likely benefit more from monotherapy with STAT3 inhibitors." (PMID 39001513, 2024). "Moreover, α-casein conditioned media reduces STAT3 reporter activity, indicating that STAT3 is a crucial transcription factor in regulating HIF-1α in breast cancer stem cells." (PMID 38990440, 2024). "In breast cancer, CSF2 could activate the Stat3 pathway in CAA via paracrine or autocrine mechanisms, leading to increased expression and secretion of CXCL3." (PMID 39497824, 2024). "In primary breast cancer, miR-146 expresses a negative feedback loop to IL-6 as a mean to inhibit the tumor progression initiated by IL-6/STAT3 pathway." (PMID 38726321, 2024). "STAT3 is the prominent mediator of TAM expansion and polarization across the TME in breast cancer." (PMID 39125273, 2024). "Leptin promotes breast cancer cell proliferation by activating STAT3; in this process, SRC-1 can be recruited to the STAT3 promoter and interact with its activation domain to enhance STAT3 signalling." (PMID 38553750, 2024). "Additionally, nobiletin has been discovered to impede cancer angiogenesis in mammary carcinoma showing estrogen receptor positivity by restraining the signaling mediated by Src, FAK, and STAT3 while fostering PXN gene expression." (PMID 38611849, 2024). "In breast cancer, PD-1/PD-L1 may affect various signaling pathways, such as PTEN/PIK3CA, ERBB2 and STAT3, affecting various biological processes of tumor cells and the interaction between tumor cells and immune cells." (PMID 37154982, 2023). "We also observed reduced STAT3 signaling in metastases vs primary breast cancer samples in all four clinical cohorts, which concurs with reported inactivating JAK2 and STAT3 mutations in metastatic/relapse samples that are not observed in primary lesions." (PMID 37463901, 2023). "These cytokines have been shown to play critical roles in regulating tumor immune tolerance, recruitment and de-differentiation of myeloid-derived suppressor cells, EMT induction, activation of STAT3, PI3K, MAPK and Rho signaling pathways, and inducing cancer stemness in breast cancer cells." (PMID 36710348, 2023). "In addition to ES, different types of STAT3 inhibitors have been applied in glioma (NCT01904123), breast cancer (NCT03195699), lymphoma (NCT01563302), etc., in clinical trials." (PMID 37759224, 2023). "In addition, MARCHF8 overexpression also promotes apoptosis and hinders tumorigenesis and metastasis of breast cancer cells by downregulating CD44 and STAT3." (PMID 36867660, 2023).
breast cancer (continued). "We identified an increased presence of phosphoproteins such as p-AKT1, p-STAT3, p-SMAD3, p-CREB1, p-p38, p-PTN11, and p-ERK1 in mammary tumors compared to the mammary gland, which should be further investigated as potential novel biomarkers in mammary carcinogenesis." (PMID 37568820, 2023). "To explore the mechanism of MLN8237 promoting PD-L1 expression, we screened JAK/STAT, PI3K/AKT and MAPK/ERK signal paths with SKBR3 breast cancer cells, and the protein levels of p-STAT1, p-STAT3, p-STAT5, p-AKT and p-ERK were detected after treatment with MLN8237." (PMID 37781397, 2023). "Insights into curcumin’s effect on mammary cancer progression were provided through the demonstration of its synergistic action with β-interferon-induced upregulation of the anti-oncogenic protein GRIM-19 and inhibition of STAT3 transcription." (PMID 37376060, 2023). "Based on these results, inhibiting STAT3 and Akt in breast cancer with higher expression levels of FGF3 could be used as a potential measure to treat breast cancer or as a complementary means for FGFR-targeted therapy." (PMID 37496658, 2023). "Although the FDA has not approved any IL-6/JAK/STAT3 pathway inhibitors for breast cancer, many of them are currently under development in preclinical and clinical investigation." (PMID 37237509, 2023). "An example is the JAK/STAT pathway, where STAT3 protein is up-regulated in a population of stem-like breast cancer cells in comparison to non-stem-like breast cancer cells." (PMID 37492743, 2023). "Furthermore, SCARA5 inhibits breast cancer cell proliferation, colony formation, invasion, and migration by inhibiting the phosphorylation of AKT, STAT3, and ERK1/2 and also induces breast cancer cell apoptosis." (PMID 37035142, 2023). "Also important in the induction of breast cancer cell migration by CXCL1 are Akt/protein kinase B (PKB), NF-κB, and STAT3." (PMID 37108425, 2023). "Here, we demonstrate that the ability of PD-L1 to induce cell-autonomous- and PD-1-induced effects is mediated through STAT3 and STAT1 activation, leading to increased tumor cell growth, CXCL8 release and cancer cell invasion in luminal A and TNBC breast cancer cells." (PMID 37830552, 2023). "STAT3 pathway supports the EMT process by stimulating specific transcription factors In previous studies, we have shown that the NF-κB/STAT3 crosstalk mediated immunosuppression by M2-TAMs in the TME of breast cancer." (PMID 36857852, 2023). "Taken together, STAT3 and AIFM2 are two unfamiliar ferroptosis-related regulators in breast cancer, suggesting that novel ferroptosis-related signals mediated by ncRNAs may be more prevailing in breast cancer." (PMID 37065473, 2023). "Moreover, TIA was shown to intercept the PI3K/Akt and STAT3 pathways in pancreatic cancer cells, diminish ERK1/2 activity in lung cancer cells, and activate the ATM/Chk2 and p38 MAPK pathways in breast cancer." (PMID 37175205, 2023). "To detect whether STAT3 mediates PRRG4-enhanced mtDNA and ATP contents in breast cancer cells, we examined the effects of Stattic (a STAT3 inhibitor) treatment on MDA-MB-231 or HCC1954 cells overexpressing PRRG4-WT." (PMID 38102641, 2023). "In socially isolated animals, the herbal product inhibited IL6/JAK/STAT3 signaling, upregulated OXPHOS signaling, suppressed the expression of RAGE ligands S100a8 and S100a9, and prevented the increase in recurrence of dormant mammary tumors." (PMID 36980301, 2023). "Doxorubicin induces p-STAT3 in human breast cancer MCF cell line (ER+, non-metastatic) and human triple negative breast cancer MDA-MB-231 cell line (metastatic)." (PMID 36902166, 2023). "This study revealed the non-canonical molecular mechanism of IL-6 secreted by breast cancer upregulated KDM2A expression in CAFs via a novel STAT3/NFκB p50 axis, which STAT3 complexed with NFκB p50 in NFκB p50 binding motif of KDM2A promoter." (PMID 37821959, 2023).
breast cancer (continued). "For example, the inflammatory cytokine IL-6 can not only induce the transformation of non-stem cells into CSCs in liver cancer, breast cancer and prostate cancer cell lines but also activate STAT3 signalling to regulate the self-renewal of CSCs." (PMID 38041196, 2023). "To follow up on our previous findings demonstrating the key roles of STAT3 and STAT1 in mediating the cell-autonomous pro-metastatic effects of PD-L1 in breast cancer cells, we next determined the impact of each of the four N-linked glycosylation sites on STAT3 and STAT1 activation." (PMID 37830552, 2023). "We have previously shown that SDC1 expression affects cancer stem cell-related pathway components, including IL-6/STAT3, Notch, and EGFR signaling pathways, in SUM-149 triple-negative inflammatory breast cancer cells, an aggressive and deadly form of breast cancer." (PMID 36980680, 2023). "Our previous reports indicated that MUC16 could induce the G2-M transition of breast cancer cells by interacting with Janus kinase 2 (JAK2), which in turn enhances the phosphorylation of STAT3 (Y705) and Aurora Kinase A." (PMID 36918912, 2023). "A recent study has revealed MORC4 could induce the expression of MID2 by recruiting STAT3 to MID2’s promoter region, leading to enhancement of the chemo-resistance to breast cancer cells." (PMID 37760252, 2023). "In addition, our data revealed that ZnPT significantly inhibited multiple aberrantly activated signaling pathways in breast cancer, including EGFR, AKT, and STAT3." (PMID 37953954, 2023). "Moreover, CDDO-Im was shown to effectively block the EGFR/signal transducer and activator of transcription 3 (STAT3)/Sox-2 signaling pathway and consequently metastasis of breast cancer." (PMID 36982173, 2023). "LncRNA versican (VCAN)-AS1 promotes breast cancer cell migration, invasion, and EMT by working as a competing endogenous RNA to inhibit miR-106a-5p, which cancer cell progression via targeting signal transducer and activator of transcription 3 (STAT3) and inhibiting the STAT3/HIF1α axis." (PMID 37583933, 2023). "Moreover, obese bASCs have an increased secretion of IL6, which has been shown to trigger cancer cell proliferation by activating the JAK/STAT3, ERK1/2 and STAT3/NFĸB pathways in multiple cancer entities including breast cancer." (PMID 36710348, 2023). "Besides, c-MYC mRNA was significantly upregulated in macrophages after CSF-1 stimulation, boosting macrophage proliferation.Via JAK1/STAT3 signaling pathway, IL-11 induces c-MYC expression to promote breast cancer bone metastasis." (PMID 36721232, 2023). "PiR-2158 significantly decreased the protein levels of IL-11 and phosphorylated STAT3 in mammary tumors, but did not change the levels of total STAT3." (PMID 37153732, 2023). "Impaired intracellular STAT3, STAT5A and STAT5B signaling has been reported in various solid tumors such as prostate, colon, glioma, head and neck tumors, melanoma, hemoblastosis and breast cancer." (PMID 36765714, 2023). "In addition to GC development being regulated by c-Myc, it also takes place in breast cancer cell proliferation as it suppresses apoptosis via upregulating the genes cyclin D1 and c-MYC with the help of the STAT3 pathway." (PMID 37514090, 2023). "Our previous studies have clearly demonstrated the role of shPCBP1-mediated EMT in the progression of mammary carcinoma in vivo and was therefore selected as an appropriate experimental context for further characterization of FAM3C/LIFR/STAT3 participation in the regulation of pathological features." (PMID 37927213, 2023). "Furthermore, considering that indirect HIF inhibitors are effective in clinical cancer therapy, we treated tumor-bearing BALB/c mice with STAT3 and PI3K/AKT inhibitors and found that the dual-targeting strategy sensitized breast cancer to cisplatin." (PMID 35236823, 2022). "Indeed, STAT3 inhibition by Stattic phenocopied miR-155 overexpression and enhanced CXCL9 production in breast cancer cells." (PMID 35925680, 2022).